DNMT1 (DNA methyltransferase 1)
Diseases named in the same sentence as DNMT1 in open-access papers (continued):
Sharing a sentence is not in itself a finding about the gene and the disease.
prostate tumor (5 papers, 2010 to 2024). "The overexpression of DNMT1 is known to promote prostate tumor formation in the transgenic adenocarcinoma of the mouse prostate (TRAMP) model." (PMID 37345101, 2023). "Recently, several reports show that in both TRAMP and Rb−/− prostate tumors, an Rb/E2F-dependent increase of DNMT1 expression and methylation activity." (PMID 20062804, 2010). "As an upregulation of Dnmt1 and an increased production of SAMe were partially observed in adjacent benign tissues, spatial analyses outline a new hypothesis that SAMe could possibly induce changes in the prostate tumour microenvironment." (PMID 30628163, 2019). "TSPYL5, DNMT-1 and DNMT-B gene expression in DU145, LNCaP and RWPE-1 cells and prostate tumor tissues was analyzed by qRT-PCR and RT-PCR." (PMID 28235398, 2017).
psoriasis (5 papers, 2018 to 2025). An autoimmune condition characterized by red, well-delineated plaques with silvery scales that are usually on the extensor surfaces and scalp. "According to a study, psoriasis patients' PBMCs express more DNMT1 than those from the healthy control group." (PMID 40182929, 2025). "It is involved in the expression regulation of psoriasis-related genes Methyltransferase DNMT1 as hemi-methylation is considered necessary for maintaining methylation." (PMID 32795328, 2020). "Similarly, a decreased DNMT1 expression was observed in blood DNA of individuals with Kawasaki disease, an acute vasculitis syndrome, whilst increased DNMT1 expression was observed in blood DNA from patients with psoriasis." (PMID 31817852, 2019). "Overexpression of DNA methyltransferase 1 (DNMT1) and global hypermethylation was also reported in psoriatic tissues and PBMCs of psoriasis patients." (PMID 30092825, 2018).
testicular germ cell tumor (5 papers, 2019 to 2025). A germ cell tumor arising from the testis.
urothelial carcinoma (5 papers, 2014 to 2022). A malignant neoplasm derived from the transitional epithelium of the urinary tract (urinary bladder, ureter, urethra, or renal pelvis). "Deepika Dhawan and his coworkers have found that DNMT1 has excellent potential as a target for invasive urothelial carcinoma therapy in human being." (PMID 27777512, 2016). "Interestingly, a HDAC inhibitor trichostatin A (TSA) has been reported to reduce DNMT1 protein in urothelial carcinoma cell lines and reduce nuclear DNMT1 while increase cytoplasmic DNMT1 in HepG2 cell." (PMID 29137356, 2017).
-thalassaemia (4 papers, 2009 to 2025). "DAXX has been found to be associated with multiple proteins involved in transcriptional repression, such as HDAC1, DNA methyltransferase 1 (DMNT1), and α-thalassaemia/mental retardation syndrome X-linked (ATRX)." (PMID 30336783, 2018).
autism spectrum disorder (4 papers, 2015 to 2025). A spectrum of developmental disorders that includes autism, and Asperger syndrome. "In the human brain, downregulation of nuclear DNMT1 is linked to Parkinson’s disease (PD) and dementia with Lewy bodies (DLB), whereas a mutation in the DNMT3a gene is linked to autism spectrum disorder (ASD) and Tatton-Brown–Rahman syndrome (TBRS)." (PMID 40940739, 2025). "Although there is no clear data on the levels of DNMT1 in autism spectrum disorders, two risk-conferring variants of DNMT1 that have been predicted to result in its over expression were reported in patients." (PMID 38125006, 2023).
brain cancer (4 papers, 2018 to 2023). A primary or metastatic malignant neoplasm affecting the brain. "During the purification of DNMT1 protein complexes, we have also noticed the presence of peptides derived from L3MBTL3, a protein that contains the three tandem repeated malignant brain tumor (MBT) domain." (PMID 29691401, 2018). "Another interesting target identified was the TSPO -(Translocator protein) that is known to be expressed exclusively in brain cancers, including GBM, and can be used for delivering drugs across the blood brain barrier along with DNA topoisomerase I (TOP1), Lipoprotein Lipase (LPL), and DNMT1." (PMID 37637064, 2023).
breast fibroadenoma (4 papers, 2012 to 2025). "Clinically, patients with BC were reported to overexpress DNMT1 compared to patients with breast fibroadenoma, and this overexpression was associated with BC development, while its downregulation inhibits proliferation and invasion of BC." (PMID 38257347, 2024). "Higher expression levels of DNMT1 have been found in patients with BC than in those with breast fibroadenoma." (PMID 38257347, 2024).
cognitive decline (4 papers, 2018 to 2024). "The DNMT1 rs2162560 A allele was observed in 21.8% of patients and this was associated with lower odds of self-reported cognitive decline in the concentration (OR = 0.45, 95% CI: 0.25–0.82, P = 0.01) and functional interference (OR = 0.48, 95% CI: 0.24–0.95, P = 0.03) domains." (PMID 31601979, 2019). "Since the loss of 5-mC is a well-known hallmark of aging brain and the loss of DNMT1 and DNMT3a proteins is known to trigger a cognitive decline in mice, these findings may indicate a premature impact of DNA methylation disturbances on SAMP8 mice cognition." (PMID 30619445, 2018).
cutaneous T cell lymphoma (4 papers, 2018 to 2024). "It was also shown that STAT3 binds to the promoter of the tyrosine phosphatase SHP-1 and recruits DNMT1 and HDAC1 to silence its transcription in cutaneous T-cell lymphoma (CTCL) and in ALK+ ALCL cell lines." (PMID 31817042, 2019).
embryonal carcinoma (4 papers, 2010 to 2015). A non-seminomatous malignant germ cell tumor characterized by the presence of large germ cells with abundant cytoplasm resembling epithelial cells, geographic necrosis, high mitotic activity, and pseudoglandular and pseudopapillary structures formation. "For example the DNA methyltransferase DNMT1 is not expressed in seminoma, however, in embryonal carcinoma it is induced." (PMID 23969837, 2013). "In contrast, CBX7 could bind to DNMT1 and induce methylation of E-cadherin and other tumor suppressor genes, not including p16, in the embryonal carcinoma cell line Tera-2." (PMID 21060834, 2010).
emphysema (4 papers, 2020 to 2023). "The expression of miR-216a and DNA methyltransferase 1 (DNMT1) was assessed in emphysema mice and COPD patients." (PMID 37822364, 2023). "The results show that the expression of miR-216a was decreased, whereas the expression of DNMT1 was increased in the lung tissue of emphysema mice and COPD patients." (PMID 37822364, 2023). "Further, in a mouse model of emphysema, DNMT1 has been highlighted to induce hypermethylation of the Bcl‐2 promoter and downregulate Bcl‐2, which is an anti‐apoptotic factor to repress cell apoptosis." (PMID 35678255, 2022). "Knockdown HOTAIR can attenuate cell apoptosis and emphysema via DNMT1 mediated hypermethylation of Bcl-2 promoter in mice." (PMID 36527094, 2022). "HPVEC apoptosis with down-regulated Bcl-2 expression, increased promoter methylation, DNMT1, Bax and Cleaved-caspase 3 expression was found in emphysema mouse model and CSE-induced HPVEC." (PMID 36527094, 2022). "Our results showed that HOTAIR mRNA levels were significantly up-regulated in the HPVEC of patients with COPD, and HOTAIR down-expression can attenuate CSE-induced cell apoptosis and emphysema via DNMT1 mediated hypermethylation of Bcl-2 promoter in mice." (PMID 36527094, 2022). "The depletion of DNMT1 by shRNA or inhibition of DNMT1 with AZA markedly reduced lung function damage, emphysema, pulmonary apoptosis, and Bcl-2 expression, suggesting that CS exposure causes emphysema, pulmonary apoptosis and hypermethylation through DNMT1." (PMID 32883320, 2020). "Cigarette-induced oxidative stress mediates pulmonary apoptosis and hypermethylation of the Bcl-2 promoter in emphysema models through DNMT1." (PMID 32883320, 2020). "Besides, the expression of DNMT1 was significantly increased in emphysema mice compared with the control group in immunohistochemistry and western blot." (PMID 37822364, 2023). "For example, DNMT1 contributed to hypermethylation of the Bcl‐2 promoter, which diminished the protein expression of Bcl‐2, thereby impairing lung function in a mouse model of emphysema." (PMID 35678255, 2022). "Following DNMT1 blockade, smoking models showed improved lung function, pulmonary apoptosis, emphysematous progression, and increased Bcl-2 protein level with less promoter methylation than emphysema mice." (PMID 32883320, 2020). "Because of the elevated DNMT1 protein level and hypermethylation of Bcl-2 in the lung tissue of emphysema subjects, we tested whether modulation of the DNMT1 protein level or activity ameliorates emphysema, pulmonary apoptosis and Bcl-2 promoter hypermethylation in mouse models." (PMID 32883320, 2020). "The expression of DNMT1 in the lung tissue of COPD patients increased and DNMT1 can mediate the hypermethylation of the Bcl-2 promoter, thus enhancing apoptosis in the lung tissue of CSE induced emphysema mice." (PMID 37822364, 2023).
gallbladder cancer (4 papers, 2021 to 2025). "DNA methyltransferase 1 (DNMT1) can mediate methylation of RUNX3 to down-regulate RUNX3 in gallbladder cancer cells." (PMID 40959280, 2025). "The expression of RUNX3 is notably diminished in gallbladder cancer tissues and cells, largely attributed to DNA Methyltransferase 1 (DNMT1)-mediated methylation." (PMID 38430423, 2024). "Existing literature suggests that DNA methyltransferase DNMT1 possesses the ability to inhibit miR-18b-5p expression through DNA methylation, thereby promoting the proliferation of gallbladder cancer." (PMID 35255904, 2022). "DNMT1 can inhibit miR-18b-5p expression through DNA methylation, thereby promoting the proliferation of gallbladder cancer." (PMID 35255904, 2022). "Long noncoding RNA PVT1 inhibits miR-18b-5p expression by recruiting DNMT1, and DNMT1 promotes miR-18b-5p methylation, thereby promoting gallbladder cancer proliferation." (PMID 34362460, 2021).
gout (4 papers, 2021 to 2025). A condition characterized by painful swelling of the joints, which is caused by deposition of urate crystals. "The results indicated that the DNMT1 rs2228611 polymorphism may be involved in the pathogenesis of gout, leading to changes in DNMT1 enzyme activity and potentially affecting DNA methylation status." (PMID 41311848, 2025). "In line with these assumptions, it is noteworthy to highlight that genome-wide association studies (GWAS) comparing gout patients to control groups have identified variants in genes encoding important players in epigenetic regulation mechanisms, such as DNA Methyl Transferase 1 (DNMT1) and lncRNAs." (PMID 34603340, 2021). "Additionally, the role of DNA methylation in gout was demonstrated through the discovery of a variant (rs2228611) in the DNA MethylTransferase 1 (DNMT1) gene whose presence is statistically increased in gout patients compared to controls." (PMID 34603340, 2021).
Intellectual disability (4 papers, 2017 to 2022). "Mutations in DNMT1 are associated with neuropathies, mutations in DNMT3A cause overgrowth syndromes with intellectual disability, and DNMT3B mutations are involved in immunodeficiency and intellectual disability." (PMID 35997367, 2022).
ischemia (4 papers, 2015 to 2022). A hypoperfusion of the BLOOD through an organ or tissue caused by a PATHOLOGIC CONSTRICTION or obstruction of its BLOOD VESSELS, or an absence of BLOOD CIRCULATION. "It has been reported that decrease of Dnmt1 expression at 4 days post-ischemia may be related to ischemia-induced delayed neuronal death." (PMID 33193709, 2020). "Both DNMT1, which functions in DNA methylation maintenance, and DNMT3A, a de novo DNA methylation enzyme, are highly expressed in lower limb arteries of PAD patients and lowest expression is present in lower limb veins of PAD patients with critical ischemia." (PMID 31440517, 2019). "Global DNA methylation increases in the brain following harmful focal ischemia, as measured by [3H]-methyl incorporation into DNA, but does not change the expression of DNMT1 or 3 (DNA methyltransferase, DNMT)." (PMID 26029158, 2015).
memory impairment (4 papers, 2020 to 2024). "Specifically, an elevated expression of DNA methyltransferase 1 (DNMT1) has been linked to memory impairment in amnesic mice." (PMID 38482343, 2024). "DNMT1 is an enzyme that catalyzes the transfer of methyl groups to DNA CpG sites, and previous research in animal models has shown that aberrant DNMT1 expression is associated with memory impairment." (PMID 38396891, 2024). "In a high methionine-induced AD rat model, DNMT1 was downregulated and tyrosine receptor kinase-induced memory impairment was observed." (PMID 38396891, 2024).
metabolic syndrome (4 papers, 2022 to 2025). A cluster of metabolic risk factors for CARDIOVASCULAR DISEASES and TYPE 2 DIABETES MELLITUS. "DNMT1 was selected as the central gene in the development of metabolic syndrome and might be a potential therapeutic target." (PMID 39819282, 2025). "Similarly, DNMT1 mRNA levels increased in patients with dyslipidemia (2.57 ± 0.87%) compared with healthy individuals (1.02 ± 0.2%)." (PMID 37372091, 2023).
metastatic melanoma (4 papers, 2019 to 2024). A melanoma that has spread from its primary site to another anatomic site. "To further determine the role of acetylation on DNMT1 protein stability, we evaluated the effect of panobinostat treatment in metastatic melanoma cell lines." (PMID 34572918, 2021). "In this study, we showed that surgically resected tumors have significantly higher DNMT1 protein expression in metastatic melanoma (stage III metastasis n = 17, p = 0.0009; stage IV metastasis n = 164, p = 0.003) compared to normal organ tissues (n = 19)." (PMID 34572918, 2021). "Using a TMA, we observed a significant decrease in ac-DNMT1 protein levels, and an inverse correlation between ac-DNMT1 and DNMT1 protein levels in metastatic melanoma patients." (PMID 34572918, 2021). "We assessed 141 stage IV metastatic melanoma patients with age, gender, organ site, and ac-DNMT1/DNMT1/TIP60/USP7 H-scores in a regression model." (PMID 34572918, 2021). "There was a significant inverse correlation between ac-DNMT1 and DNMT1 protein levels in stage IV metastatic melanoma (r = −0.18, p = 0.02, n = 164)." (PMID 34572918, 2021). "In this study, we systematically investigated the translational utility of DNMT1/ac-DNMT1 protein levels in cutaneous metastatic melanoma." (PMID 34572918, 2021). "However, it is unclear how DNMT1 protein regulators and post-translational modifications determine DNMT1 expression to influence metastatic melanoma outcomes." (PMID 34572918, 2021). "To determine factors that may be associated with enhanced DNMT1 expression, we investigated the copy number variation (CNV) dataset of metastatic melanoma patients from the TCGA SKCM project." (PMID 34572918, 2021). "The higher expression of DNMT1 and EZH2 is concordant with previous observations in BRAF-mutated cells, such as it is the case for WM266-4, described to participate in the hypermethylated phenotype of metastatic melanoma cells (and personal observations)." (PMID 30651148, 2019). "However, only 16.6% (n = 61) of metastatic melanoma samples had a gain in CNV for DNMT1." (PMID 34572918, 2021). "Thus, there may be other regulatory mechanisms enhancing DNMT1 expression or promoting its protein stability in metastatic melanoma, such as specific PTMs." (PMID 34572918, 2021). "Furthermore, significantly higher DNMT1 protein expression was observed in metastatic melanoma." (PMID 34572918, 2021). "There were significant positive correlations between USP7 and ac-DNMT1 protein levels in both stage III (r = 0.5, p = 0.04) and stage IV (r = 0.74, p < 0.0001) metastatic melanoma samples." (PMID 34572918, 2021). "The role of post-translational modifications (PTM) of the key epigenetic factor DNMT1 protein has not been well explored in cutaneous metastatic melanoma progression." (PMID 34572918, 2021). "Additionally, ac-DNMT1 protein levels were also significantly positively correlated with TIP60 (r = 0.6, p < 0.0001) and USP7 (r = 0.74, p < 0.0001) protein levels in stage IV metastatic melanoma (n = 164)." (PMID 34572918, 2021).
retinal degeneration (4 papers, 2013 to 2025). Degeneration of the retina. "In mice, retina specific deletion of DNA methyltransferase 1 (Dnmt1) disrupts retinal differentiation and leads to rapid retinal degeneration, with effects that are particularly pronounced in photoreceptors." (PMID 24179439, 2013).
steatosis (4 papers, 2012 to 2023). Increased lipid within the cytoplasm of cells. "Taken together, these results demonstrate that in spite of decrease in hepatic Dnmtase activity in mice fed the alcohol diet, Dnmt1 hypomorphic mice are relatively resistant to alcohol-induced steatosis and liver damage compared to the wild type mice." (PMID 22905112, 2012).
thymoma (4 papers, 2016 to 2024). A neoplasm arising from the epithelial cells of the thymus. "In our cohort, DNMT1 and DNMT3B do not show different methylation levels among different tissues, so we cannot hypothesize the involvement of the methylation of these genes in thymoma-associated myasthenia gravis pathogenesis." (PMID 27999265, 2016).
ulcerative colitis (4 papers, 2022 to 2025). An inflammatory bowel disease involving the mucosal surface of the large intestine and rectum. "We found that DNMT3A mRNA levels, but not DNMT3B nor DNMT1, were significantly reduced in both inflamed and non inflamed samples from Crohn ́s disease (CD), but also from ulcerative colitis patients, compared to healthy individuals." (PMID 36271073, 2022).
alcohol abuse (3 papers, 2017 to 2025). The use of alcoholic beverages to excess, either on individual occasions ("binge drinking") or as a regular practice. "Expression of DNMT1, DNMT3B and DNMT3L was identified to be negatively correlated with the expression of TNFRSF12A in 116 HCC with alcohol abuse (r <−0.22, p < 0.01)." (PMID 31998364, 2019).
Arthritis (3 papers, 2022 to 2025). Inflammation of a joint. "Inhibition of DNMT1 has been carried out in several areas of research such as in arthritis and ankylosing spondylitis." (PMID 37199639, 2023). "Similarly, Wutou decoction plays a role in the treatment of arthritis by targeting DNMT1 in the CIA rat model." (PMID 40650121, 2025). "The function of UHRF1 in maintenance of DNA methylation is thought to be mediated through DNMT1, although whether suppressive functions of Uhrf1 in arthritis can be completely mediated through Dnmt1 is unclear." (PMID 35472067, 2022).
chondrosarcoma (3 papers, 2017 to 2020). A malignant cartilaginous matrix-producing mesenchymal neoplasm arising from the bone and soft tissue. "In this study, we found that expression of miR-454-3p increased after HOTAIR knockdown, and we found that HOTAIR recruited EZH2 and DNMT1 to the promoter of miR-454-3p, increased DNA methylation at the miR-454-3p promoter regions and repressed miR-454-3p expression in chondrosarcoma." (PMID 28182000, 2017).